SNORD127 (small nucleolar RNA, C/D box 127)
Gene: Small nucleolar RNA gene on chromosome 14 (45,110,883 to 45,110,968, forward strand). Ensembl gene ENSG00000239043.
Gene Ontology:
Biological process: RNA processing
Cellular component: nucleolus
Homologues: Orthologues: chimpanzee SNORD127 (99% identical), macaque SNORD127 (98% identical), guinea pig SNORD127 (94% identical), pig SNORD127 (93% identical), rabbit SNORD127 (92% identical), mouse Gm25970 (87% identical), rat Snord127 (87% identical), tropical clawed frog SNORD127 (78% identical).